ASF1B (anti-silencing function 1B histone chaperone)
Diseases named in the same sentence as ASF1B in open-access papers (continued):
Sharing a sentence is not in itself a finding about the gene and the disease.
tumor (28 papers, 2015 to 2025). "ASF1B is linked to multiple categories of immune infiltrating cells and immune signaling pathways, thereby impacting tumor progression through modifications in immune infiltration dynamics." (PMID 40041497, 2025). "Unlike its isoform ASF1A, which is more involved in transcriptional regulation and senescence, ASF1B is predominantly associated with cell proliferation and tumor progression." (PMID 40944429, 2025). "For example, ASF1B was significantly and positively associated with tumor killer cells (e.g., CD8+ T cells and NK cells) and APC co-inhibition, and Inflammation promoting." (PMID 38164276, 2024). "ssGSEA, TMB, TIDE and IMvigor210 cohort were used to explore and validate the association of ASF1B to tumor immunity." (PMID 38164276, 2024). "Overall, our study revealed that ASF1B was overexpressed in LUAD tumor tissues, and was significantly associated with the progression, prognosis, and immunotherapy effect for LUAD." (PMID 38164276, 2024). "Histone H3/H4 chaperone anti-silencing function 1 B (ASF1B) has a tight association with the initiation and development of tumours." (PMID 36947060, 2023). "ASF1B is closely implicated in the initiation and development of numerous tumours through regulating cell proliferation." (PMID 36947060, 2023). "GSEA and GSVA suggested that ASF1B was involved in tumor-associated biological processes, including the cell cycle, DNA replication, base excision repair, mismatch repair, RNA degradation, ubiquitin-mediated proteolysis, and nucleotide excision repair." (PMID 35360875, 2022). "Gene set enrichment analysis (GSEA) and gene set variation analysis (GSVA) were performed to probe the tumor-associated biological processes of ASF1B in HCC." (PMID 35360875, 2022). "In the tumor tissue, the expression of ASF1B was associated with tumor grade, T stage, and TNM stage." (PMID 35360875, 2022). "We further explored the potential associations of ASF1B with tumor-infiltrating immune cells and the efficacy of immunotherapy using multiple online public databases." (PMID 35360875, 2022). "Genetic, epigenetic, microsatellite instability (MSI), and tumor mutational burden (TMB) analysis showed that ASF1B was regulated by single or multiple factors." (PMID 34568067, 2021). "Finally, we also explored the potential associations between ASF1B expression levels and tumor immune infiltration as well as the efficacy of immunotherapy." (PMID 38164276, 2024). "Subsequently, we also compared the tumor mutation burden (TMB) in the different ASF1B level groups." (PMID 38164276, 2024). "In addition, univariate analyses revealed that tumor size (>5 cm), N stage (N2/N3), M stage (M1) and ASF1b expression (High) were independently associated with poor OS." (PMID 35399734, 2022). "In addition, ASF1B expression levels were found to be associated with tumor immune infiltration in THCA, KIRC, LGG, and LIHC, and with tumor microenvironment in BRCA, LUSC, STAD, UCEC, and KIRC." (PMID 34490109, 2021). "Furthermore, ASF1B expression is associated with poor prognosis in main tumor types and may be an independent prognostic factor in many malignancies." (PMID 40770782, 2025). "Furthermore, loss of ASF1b was efficient to suppress subcutaneous xenograft tumor growth in vivo." (PMID 35399734, 2022). "Based on these works, biological function experiments were conducted, proving that ASF1B contributes to tumor cell proliferation, clone formation, invasion, and migration in vitro." (PMID 40041497, 2025). "These in vivo results suggest that ASF1B knockout inhibits subcutaneous tumor formation by MKN45 cells in NSG mice." (PMID 40041497, 2025). "In clinical tissue samples, ASF1B mRNA levels were significantly higher in tumor tissues compared to adjacent non‐cancerous tissues (p < 0.001)." (PMID 40944429, 2025).
tumor (continued). "Biological function tests provided that ASF1B contributes to tumor cell proliferation, colony formation, invasion and migration, and plays an important role in the progression of GC in vivo." (PMID 40041497, 2025). "Based on this finding, we can try to design small molecule proteins that target the binding sites of the two to block the binding of the two, and explore the role of ASF1B as an anti-tumor target more safely and effectively." (PMID 40041497, 2025). "IHC staining showed stronger ASF1B protein expression in tumor sections, confirmed by semi‐quantitative IRS analysis (p < 0.001)." (PMID 40944429, 2025). "We observed high expression state of ASF1B in LUAD tumor tissues in multiple datasets (TCGA, GSE10072 and GSE32863), and this high expression state had a negative impact on patient outcome (TCGA, GSE30219, GSE31210, GSE42127, GSE68465 and GSE72094)." (PMID 38164276, 2024). "In the 57 paired LUAD tumor and normal tissue samples, as expected, ASF1B remained highly expressed in the tumor tissue." (PMID 38164276, 2024). "ASF1B overexpressing cells significantly promoted the ability of tumor cells to penetrate the transwell compartment when compared with controls." (PMID 38164276, 2024). "In the TCGA-LUAD project, we first compared ASF1B expression between the two groups in unpaired LUAD tumor (n=535) and normal tissue samples (n=59), and found that compared to normal tissues, tumor tissues expressed significantly more ASF1B." (PMID 38164276, 2024). "Disrupting ASF1B significantly suppresses tumor growth by G2/S stage cell cycle arrest and stimulates the apoptosis pathway." (PMID 35360875, 2022). "Previous studies have reported that ASF1B functions as an oncogene to promote tumor growth by participating in the cell cycle." (PMID 35360875, 2022). "But we are currently conducting basic experiments in vivo and vitro to investigate how the aberrant elevation of ASF1B influences tumor behavior and the TIME in HCC." (PMID 35360875, 2022). "Several studies have suggested that anti-silencing function 1 B (ASF1B) can serve as a good potential marker for predicting tumor prognosis." (PMID 35875094, 2022). "Following that, we looked into the association between DHRS7 expression and tumor stage and discovered that ASF1B expression was substantially correlated with tumor stage in seven malignancies, including KIRC, KIRP, LUSC, READ, SKCM, STAD, and THCA." (PMID 36276963, 2022). "These in vivo results support that ASF1b improves tumor vascular function and promotes tumor growth in GC." (PMID 35399734, 2022). "The results showed that high ASF1B expression led to poorer overall survival and the potential to shorten the interval for tumor progression, tumor recurrence, and death." (PMID 35280822, 2022). "The interrelationships between ASF1B expression and tumor immunological characteristics were analyzed by multiple databases." (PMID 35360875, 2022). "The factors significantly associated with OS were tumor size (5 cm) (p = 0.014), tumor number (p = 0.024), vascular invasion (p = 0.018), T stage (p < 0.001), N stage (p = 0.033), TNM stage (p < 0.001), and ASF1B expression (p < 0.001)." (PMID 35360875, 2022). "The results showed that the mRNA and protein levels of ASF1B were aberrantly high in HCC, and Western blotting of ASF1B protein levels in a normal liver cell line and tumor cell lines confirmed these results." (PMID 35360875, 2022). "The factors significantly associated with PFS were tumor size (5 cm) (p = 0.001), vascular invasion (p = 0.046), T stage (p < 0.001), TNM stage (p < 0.001), and ASF1B expression (p < 0.001) in the validation set." (PMID 35360875, 2022). "This evidence strongly suggests that SNHG3/miR-214-3p/ASF1B axis promotes HCC recurrence by activating tumor immune tolerance and escape, and PD-1 plays an crucial role in this process." (PMID 34336642, 2021).
tumor (continued). "Next, we employed the CIBERSORT algorithm to assess relationships between immune cell infiltration and ASF1B expression in tumor and normal tissue samples." (PMID 34568067, 2021). "Second, data from normal tissues in the GTEx database and data from TCGA tumor tissues were integrated to analyze the differences in ASF1B expression in 27 tumors." (PMID 34490109, 2021). "High ASF1B expression has been shown to affect ccRCC tumor staging and tumor grading via the AKT/P70 S6K1 pathway, leading to poor prognosis." (PMID 34472711, 2021). "Our study also found that in most tumors, ASF1B expression correlated with tumor stage; it was particularly relevant in distinguishing between stage I and stage IV tumors." (PMID 34472711, 2021). "Our results suggest that ASF1B expression is closely correlated with tumor immune infiltration and therefore affects patient prognosis and provides a new immunotherapeutic target for the treatment of patients with various types of tumors." (PMID 34472711, 2021). "We further found that the role of ASF1B in the infiltration of different types of immune cells varied across tumor types." (PMID 34472711, 2021). "We also explored tumor infiltration levels among tumors with different somatic copy number alterations for ASF1B." (PMID 35087760, 2021). "After the correlation coefficients were adjusted by tumor purity, the results showed that the ASF1B expression level was significantly correlated with the majority of immune marker sets of various immune cells in HCC." (PMID 35087760, 2021). "The CIBERSORT algorithm was used to evaluate immune microenvironment composition, and distinct correlations between ASF1B expression and immune cell infiltration were evident when comparing tumor and normal tissue samples." (PMID 34568067, 2021). "We found a slightly positive correlation between ASF1B expression and tumor purity (r = 0.191, P = 3.41E-04)." (PMID 35087760, 2021). "In MESO, high ASF1B expression was negatively correlated with neutrophil infiltration (p = 0.009) and low levels of neutrophils in tumor tissue leaded to poor patient prognosis (p = 0.001)." (PMID 34472711, 2021). "Compared with that in adjacent tissues, ASF1B was remarkably increased in tumor tissues (p < 0.05, n = 12)." (PMID 32848135, 2020). "More than half of the genes were not DE in any tumor type, while seven genes (C7, ADH1B, HSPB6, FXYD1, PLAC9, TMEM132A and ASF1B) were DE in all tumor types." (PMID 26655252, 2016). "For example, antisilencing function 1B histone chaperone (ASF1B) was upregulated in all the 13 tumor types." (PMID 26655252, 2016). "ASF1B plays a significant role in the tumor microenvironment." (PMID 40041497, 2025). "Additionally, we observed that ASF1B is involved in the tumor microenvironment, where ASF1B knockdown increases CD8+ T cell infiltration, indicating a negative correlation with immune activation." (PMID 40041497, 2025). "ASF1B’s involvement in tumor cyclin regulation was investigated." (PMID 40041497, 2025). "Interestingly, in HER2+ tumors, ASF1B was inversely correlated with macrophage presence—possibly indicating suppression of M2‐type tumor‐promoting macrophages." (PMID 40944429, 2025). "Moreover, ASF1B expression in tumor and adjacent tissues from 4 patients was confirmed to be upregulated at both protein and mRNA levels by Western blot and RT-qPCR." (PMID 40041497, 2025). "ASF1B might be able to serve as a novel molecular marker to predict patient prognosis and a novel target for tumor therapy." (PMID 38164276, 2024). "Thus, we performed univariate and multivariate Cox regression analysis using age, sex, new tumours developed after the initial treatment, tumour status, radiation therapy and ASF1B expression as variables." (PMID 36947060, 2023). "So in LGG, does ASF1B play a regulatory role in tumour by regulating TLK1?" (PMID 36947060, 2023).
tumor (continued). "Furthermore, we explored the correlations of ASF1B expression with genetic markers of various immune cells after tumor purity adjusting." (PMID 35360875, 2022). "In the present study, by incorporating data from a public databases and our tumor center, we found that ASF1B expression was higher in tumor tissue compared to paracancerous normal tissues and that the high expression of ASF1B predicted poor outcome in HCC patients." (PMID 35360875, 2022). "However, there are no comprehensive reports about the expression and prognostic value of ASF1B and its correlation with tumor immunity in HCC." (PMID 35360875, 2022). "In addition to affecting the tumor cell intrinsic features, it is reported that ASF1B can also have an impact on the tumor microenvironment by promoting the infiltration of immune cells." (PMID 35360875, 2022). "FOXP3 also acts as a target of ASF1B, which could be involved in tumor immune escape and tumor cell proliferation." (PMID 35174076, 2022). "Furthermore, BALB/C nude models were established using stable AAV-shRNA-ASF1b AGS cells or AAV-shRNA vector AGS cells to assess how ASF1b knockdown suppresses tumor growth." (PMID 35399734, 2022). "In addition, high ASF1B expression is related to immunosuppressive tumor microenvironment characteristics with high expression of T cell exhaustive markers in HCC." (PMID 35360875, 2022). "Thus, the expression of PI3K, AKT, mTOR and their phosphorylation level was determined in our study in order to investigate the role of PI3K/AKT/mTOR pathway in the anti-tumor effect of ASF1b-si." (PMID 35399734, 2022). "Further systematic and comprehensive analysis of public databases revealed that ASF1B was also correlated with immune cell infiltration and activation in the tumor microenvironment of HCC and that it could predict the efficacy of immunotherapy." (PMID 35360875, 2022). "Our results also suggested that ASF1B may be an independent prognostic factor in multiple cancers and that high ASF1B expression is relatedto poor prognosis in major tumor types." (PMID 34472711, 2021). "In further analysis it’s also found that ASF1B may regulate tumor immune patterns in various tumors by regulating the expression of specific immune checkpoint genes." (PMID 34490109, 2021). "Based on both previous studies and our own findings, we hypothesize that, in tumor types where ASF1B expression is positively correlated with TMB, high ASF1B expression, and high expression of TMB and MSI predict better prognosis and response to ICI treatment." (PMID 34472711, 2021). "It’s suggested that ASF1B may alter the tumor microenvironment or the degree of tumor immune cell infiltration." (PMID 34490109, 2021). "Further analysis of the relationship between ASF1B expression and immune checker gene expression suggested that ASF1B may regulate tumor immune patterns in most tumors by regulating the expression levels of specific immune checker genes." (PMID 34490109, 2021). "Recent studies have shown that anti-silencing function 1B (ASF1B) may be a new proliferative marker for tumor diagnosis and prognosis." (PMID 35087760, 2021). "In the cell invasion experiment of MHCC97H and Hep3B cells, ASF1B knockdown could significantly reduce the invasion ability of tumor cells." (PMID 35087760, 2021). "Our results also suggest that ASF1B may be an independent prognostic factor in multiple cancers and that high ASF1B expression is related to poor prognosis in major tumor types." (PMID 34472711, 2021). "As tumor purity has an important influence on immune infiltration levels, partial immune genetic markers with COR greater than 0.3 after tumor purity adjustment were selected, and RT-qPCR was used to verify whether their expression was affected by ASF1B." (PMID 34336642, 2021).
tumor (continued). "Based on above results, it’s suggested that in terms of the tumor immune microenvironment, ASF1B expression levels were significantly negatively correlated with the immune score in BRCA, LUSC, STAD, UCEC while significantly positively correlated with the immune score in KIRC." (PMID 34490109, 2021). "These discoveries may contribute to clarifying the role of ASF1B in tumor development and provide new regulatory targets for more precise and personalized immune antitumor strategies." (PMID 34472711, 2021). "Previously study found that ASF1B may change the tumor microenvironment and changes the percentage of the macrophage and some other immune cells such as dendritic cell, monocyte and T cells regulatory (Tregs)." (PMID 34490109, 2021). "It’s suggested that in these tumors, ASF1B may regulate the tumor immune pattern by regulating the expression levels of specific immune checkpoint genes." (PMID 34490109, 2021). "Immunohistochemical analysis of ASF1B expression in HCC tumor tissues and adjacent tissues showed strong ASF1B staining in tumor tissues, and protein western blot analysis also showed stronger ASF1B bands in tumor tissues, thus confirming the high expression of ASF1B in HCC tumor tissues." (PMID 35087760, 2021). "Upregulation of ASF1B was positively correlated with tumor size (p = 0.0108)." (PMID 32848135, 2020). "Furthermore, we established two murine models using stable ASF1B-shRNA HeLa cells or normal HeLa cells following AAV-shRNA-ASF1B administration to evaluate how suppression of ASF1B affects tumor growth." (PMID 32848135, 2020). "This may be a potential mechanism by which ASF1B regulates the tumor microenvironment of GC." (PMID 40041497, 2025). "Moreover, we proposed that ASF1B may influence the tumor immune microenvironment, thereby modulating immune cell infiltration patterns." (PMID 40944429, 2025). "In addition, although the comparison of TMB was not different between the two subsets, MATH analysis revealed that the high-ASF1B group exhibited higher abundances of tumor heterogeneity, which is generally an indicator for poor clinical outcomes in multiple malignances, including HCC." (PMID 35360875, 2022). "However, the specific role of ASF1B in each tumor type should be further investigated." (PMID 34472711, 2021). "Meanwhile, the high expression of ASF1B was closely related to advanced TNM stage, larger tumor size and more lymph node metastases in PDAC patients, suggesting that ASF1B upregulation contributes to the progression of PDAC." (PMID 36114946, 2023). "CAF-1 (in particular CHAF1B) expression in a wide range of tumours displays a strong correlation with the prototype cell proliferation marker Ki-67 and other proliferation markers (PCNA, MCMs, and ASF1b)." (PMID 34073937, 2021). "Herein, we determined that in LUAD cells, ASF1B can indirectly regulate CKS1B, POLE3, and DHFR expression, and we found it positively correlated with the expression of these genes in most tumor and normal tissue samples." (PMID 34568067, 2021). "Above results validated our hypothesis that ASF1B, as an important cell cycle regulator, may affect the HCC tumor immunity." (PMID 35360875, 2022). "Thus, in the present study, we evaluated ASF1B mRNA levels using different databases, and we evaluated protein levels by immunohistochemical analysis in HCC tumor and paracarcinoma tissues from patients treated at our clinical center." (PMID 35360875, 2022). "ASF1A, not ASF1B, regulates histone H3K56Ac levels and is increased in many tumor tissue types together with H3K56Ac levels." (PMID 26336826, 2015). "TIICs in the tumor microenvironment also influence tumor prognosis; for example, patients with thymoma with high infiltrating levels of B, CD4+ and dendritic cells (DCs) have a better prognosis and may be partially regulated by the ASF1B gene." (PMID 35928818, 2022). "However, the role of ASF1B in HCC tumor proliferation and migration has not been systematically studied." (PMID 35087760, 2021).
tumor (continued). "Furthermore, ASF1B levels, but not ASF1A levels, have a highly significant positive correlation with tumor size, tumor grade, and mitotic cell number." (PMID 35360875, 2022).